MAP3K8 (mitogen-activated protein kinase kinase kinase 8)
Description:
Required for lipopolysaccharide (LPS)-induced, TLR4-mediated activation of the MAPK/ERK pathway in macrophages, thus being critical for production of the pro-inflammatory cytokine TNF (TNF) during immune responses. Involved in the regulation of T-helper cell differentiation and IFNG expression in T-cells. Involved in mediating host resistance to bacterial infection through negative regulation of type I interferon (IFN) production. In vitro, activates MAPK/ERK pathway in response to IL1 in an IRAK1-independent manner, leading to up-regulation of IL8 and CCL4. Transduces CD40 and TNFRSF1A signals that activate ERK in B-cells and macrophages, and thus may play a role in the regulation of immunoglobulin production. May also play a role in the transduction of TNF signals that activate JNK and NF-kappa-B in some cell types. In adipocytes, activates MAPK/ERK pathway in an IKBKB-dependent manner in response to IL1B and TNF, but not insulin, leading to induction of lipolysis. Plays a role in the cell cycle. Isoform 1 shows some transforming activity, although it is much weaker than that of the activated oncogenic variant.
Synonyms: TPL-2; COT; ESTF; EST; c-COT; MEKK8; AURA2; TPL2
Tractability: Small molecule: a drug acting on it is in phase 2 or 3 trials; a structure with a bound ligand is known; a high-quality ligand is known; it belongs to a druggable protein family. PROTAC: its protein half-life has been measured; a small molecule that binds it is known.
Target class: Enzyme; STE protein kinase STE11 family; Kinase; STE protein kinase group; Protein Kinase
Chemical probes: CHEMBL491228, cyanoquinoline 11
Gene: Protein-coding gene on chromosome 10 (30,433,473 to 30,461,833, forward strand). Ensembl gene ENSG00000107968.
Subcellular location: Cytoplasm
Subcellular location (Human Protein Atlas): Cytosol
Pathways (Reactome):
Immune System: CD28 dependent PI3K/Akt signaling; MAP3K8 (TPL2)-dependent MAPK1/3 activation
Gene Ontology:
Molecular function: MAP kinase kinase kinase activity; protein binding; protein serine/threonine kinase activity; ATP binding; magnesium ion binding; protein kinase activity; protein serine kinase activity
Biological process: MAPK cascade; positive regulation of inflammatory response; protein phosphorylation; T cell costimulation; signal transduction
Cellular component: cytoplasm; cytosol
Genetic constraint (gnomAD): Loss-of-function variants: 14 observed, 37.75 expected, observed/expected ratio (o/e) 0.37, 90% interval 0.24 to 0.58. The upper end of that interval is the gene's LOEUF score, 0.58, which puts it in group 2 of 6, group 1 being the genes least tolerant of losing a copy. Missense variants: 352 observed, 519.97 expected, observed/expected ratio (o/e) 0.68, 90% interval 0.62 to 0.74. Synonymous variants: 202 observed, 197.32 expected, observed/expected ratio (o/e) 1.02, 90% interval 0.91 to 1.15.
Homologues: Orthologues: chimpanzee MAP3K8 (99% identical), macaque MAP3K8 (99% identical), dog MAP3K8 (97% identical), pig MAP3K8 (96% identical), rat Map3k8 (94% identical), guinea pig MAP3K8 (94% identical), mouse Map3k8 (93% identical), rabbit MAP3K8 (93% identical), tropical clawed frog map3k8 (71% identical), zebrafish map3k8 (60% identical). Paralogues in human: TNIK (22% identical), MAP4K4 (21% identical), SLK (21% identical), MINK1 (21% identical), STK10 (21% identical), MAP3K19 (21% identical), STK26 (20% identical), TAOK1 (20% identical), TAOK2 (20% identical), PAK3 (20% identical), STK25 (20% identical), MAP4K3 (19% identical), and 23 more.
Diseases named in the same sentence as MAP3K8 in open-access papers:
MAP3K8 is named in the same sentence as 150 diseases in open-access papers, as found by Europe PMC text mining. Sharing a sentence is not in itself a finding about the gene and the disease. The quoted sentences say what the papers report.
breast cancer (19 papers, 2004 to 2025). A primary or metastatic malignant neoplasm involving the breast. "In contrast, in lung cancer and breast cancer, MAP3K8 has been reported to be a tumor suppressor, patients with high MAP3K8 expression showed better prognosis." (PMID 40831931, 2025). "Overexpression of MAP3K8 was found in several tumor types, including skin cancer, prostate cancer, breast cancer, squamous cell carcinoma, ovarian cancer, hepatocellular carcinoma, and colorectal cancer." (PMID 35004849, 2021). "MAP3K8 was identified as an oncogene in endometrial cancer, breast cancer, colon cancer, renal cancer, gastric cancer, and nasopharyngeal carcinoma, but it is a tumor suppressor gene in lung and intestinal cancers as well." (PMID 31552087, 2019). "Additionally, a study has shown that IL-22 released by Th17 cells can activate the MAP3K8 signaling pathway in BC cells, which in turn activates the STAT3 and AP-1 pathways, thereby increasing breast cancer aggressiveness." (PMID 41597595, 2025).
melanoma (19 papers, 2014 to 2023). A malignant, usually aggressive tumor composed of atypical, neoplastic melanocytes. "The COT/TPL2 (MAP3K8) expression has also been observed to cause de novo resistance in melanoma cell lines." (PMID 37645429, 2023). "Mutations in MAP3K8 are present in about 1.5% of all melanoma patients, frequently in Spitz nevi (in about 33% cases)." (PMID 32605090, 2020). "Moreover, MAP3K8 expression is also associated with resistance to chemotherapeutic agents in thyroid cancer and melanoma." (PMID 36768307, 2023). "As required for resistant melanoma cell survival, MAP3K8 is a potential therapeutic target in this specific setting." (PMID 35966590, 2022). "Enforced expression or amplification of MAP3K8 promotes BRAFi and MEKi resistance in melanoma cells, and MAP3K8 upregulation is observed in a group of disease-progressed melanoma patients on BRAFi or MEKi treatment." (PMID 35966590, 2022). "Previous studies have revealed that genetic alterations of MAP3K8 were involved in tumorigenic progression in colorectal cancer, melanomas, and lung cancer." (PMID 34567061, 2021). "Administering BRAF inhibitors in the case of primary MAP3K8 overexpression further increases the expression of this protein, which in turn stimulates the proliferation of melanoma cells." (PMID 32605090, 2020). "The usage of MEK and EKR inhibitors has been suggested as a strategy for targeting MAP3K8 melanoma dependence." (PMID 32605090, 2020). "Moreover, MAP3K8 activation is also known to be a critical driving factor for drug resistance in various cancers, including melanoma, chronic myeloid leukemia, and thyroid cancer stem cells." (PMID 36768307, 2023). "We anticipate that the public availability of CICERO will also lead to improved fusion analysis for adult cancer RNA-seq data, as demonstrated through our re-analysis of TCGA GBM in this study and our recent discovery of MAP3K8 C-terminal truncation fusion in 2% of TCGA melanoma samples." (PMID 32466770, 2020). "Thus, HGSC with high MAP3K8 protein levels mimic the pathological situation observed in melanoma, which become resistant to anti-BRAF therapy." (PMID 26456302, 2015). "Interestingly, rearrangements and amplification of the MAP3K8 gene leading to increased levels of the truncated, active form of this protein are detected in approximately 15% of melanomas without driver mutations, such as BRAF, NRAS, or NF1." (PMID 35565444, 2022). "Therefore, MAP3K8 rearrangement could be a biomarker to identify melanoma patients that may benefit from MEK or ERK inhibitors." (PMID 34567061, 2021). "This interaction activates mitogen-activated protein kinase kinase kinase 8 (MAP3K8), also termed tumour progression locus 2 (TPL2), which conversely stimulates the transcription factor ETS translocation variant 4 (ETV4), leading to induction of MMP25 and promoting melanoma lung metastasis." (PMID 32722137, 2020). "This suggests that resistance to vemurafenib of melanomas without upregulation of CD47 may be primarily due to mechanisms other than reactivation of ERK, such as overexpression of MAP3K8 (COT) and switch of melanoma cells towards a more mesenchymal phenotype." (PMID 29050218, 2017).
lung carcinoma (14 papers, 2015 to 2025). "Furthermore, in lung cancer, high levels of MAP3K8 expression have been associated with chemotherapy resistance and worse clinical outcomes." (PMID 39901302, 2025). "MAP3K8 (Serine/threonine protein kinase tumour progression locus 2) has been widely reported to be an important signal for inflammatory mediators, and mutational activation of MAP3K8 may be involved in the formation of lung cancer." (PMID 32019546, 2020). "We describe here the results of MAP3K8 knockdown in the A549 lung cancer cell line, the BEAS-2B epithelial cell line and normal human bronchial epithelial (NHBE) cells following IL-1β stimulation." (PMID 39030600, 2024).
hepatocellular carcinoma (13 papers, 2004 to 2025). A malignant tumor that arises from hepatocytes. "miR-589-5p is a well-established cancer-associated miRNA, found to inhibit MAP3K8 in hepatocellular carcinoma, regulate tumor growth in HCC by targeting MIG-6, and act as tumor suppressor in prostate cancer." (PMID 34805186, 2021). "In hepatocellular carcinoma, MAP3K8 has been reported to promote tumor progression through regulating PD-L1+ macrophage infiltration, indicating its immune regulatory role." (PMID 40831931, 2025). "It is declared that ALKBH5, as an oncogene, enhances macrophage recruitments via the alteration of m6A modification of MAP3K8 and promotes hepatocellular carcinoma metastasis." (PMID 38481816, 2024). "Research had also found that ALKBH5 regulated the expression of MAP3K8 in hepatocellular carcinoma (HCC) cells and modulated IL-8 expression through the JNK and ERK pathways, promoting macrophage recruitment." (PMID 39220683, 2024). "To evaluate the effect of ALKBH5 on the tumor immunosuppressive microenvironment, we constructed the mouse hepatoma cell line H22 with stable ALKBH5 knockdown and stable MAP3K8 overexpression." (PMID 35982895, 2022). "miR-589-5p resulted a good inhibitor of MAP3K8 and suppressor of CD90+ cancer stem cells in hepatocellular carcinoma." (PMID 29423032, 2018).
colorectal cancer (10 papers, 2017 to 2025). A primary or metastatic malignant neoplasm that affects the colon or rectum. "For instance, in colorectal cancer (CRC), up-regulation of MAP3K1, MAP3K4, MAP3K7, and MAP3K8 has been associated with tumor progression, activation of oncogenic signaling pathways, and poor prognosis, similar to findings in GC." (PMID 39901302, 2025). "REG1A, CK20, and MAP3K8 gene expression was shown to be related to early-onset colorectal cancer formation." (PMID 33507673, 2021). "Overexpression of MAP3K8, also known as tumor progression locus 2 (TPL2), is correlated with poor prognosis and metastasis in patients with colorectal cancer." (PMID 32986377, 2020). "In conclusion, microRNA-375 might function as a tumor-repressive gene to inhibit cell proliferation, mainly through targeting both JAK2/STAT3 and MAP3K8/ERK signaling pathways in colorectal cancer." (PMID 28186962, 2017).
Obesity (10 papers, 2012 to 2022). Accumulation of substantial excess body fat. "Based on the association of higher MAP3K8 expression with both BMI and enhanced levels of IL-1ß responsive genes in human adipose tissue, we set out to determine if MAP3K8 causally affects obesity and adipose tissue inflammation in vivo." (PMID 24586913, 2014). "Another study reported that MAP3K8 regulates obesity-associated inflammation and insulin resistance." (PMID 24586913, 2014). "First, we determined the association of MAP3K8 (TPL2/COT) expression in human adipose tissue with measures of obesity (BMI), adipose tissue inflammation (cytokine expression) and insulin resistance (plasma insulin)." (PMID 24586913, 2014). "We found that human MAP3K8 expression in adipose tissue is indeed associated with obesity." (PMID 24586913, 2014). "As we found in the survival analyses, 5 DE mRNAs (SORCS1, FLRT3, HIBADH, CATSPER1, and MAP3K8) and 5 DE miRNAs (hsa-miR-3130-2, hsa-miR-148b, hsa-miR-2681, hsa-miR-4487, and hsa-miR-3613) of obesity-related ccRCC were found in VAT." (PMID 34621242, 2021). "MAP3K8 (also referred to as TPL2) was previously shown to be overexpressed in subcutaneous adipose (SQ) tissue from patients with obesity and this correlated with elevated levels of the inflammatory proteins IL-1β, IL-6, and IL-8." (PMID 31798691, 2019). "We used human adipose tissue biopsies to study the relationship of MAP3K8 expression with markers of obesity and expression of pro-inflammatory cytokines (IL-1β, IL-6 and IL-8)." (PMID 24586913, 2014). "MAP3K8 (TPL2/COT) is an important signal transductor and activator of pro-inflammatory pathways that has been linked to obesity-induced adipose tissue inflammation." (PMID 24586913, 2014). "Three prior studies have provided contradictory evidence for the role of MAP3K8 in obesity-induced inflammation and metabolic dysfunction." (PMID 24586913, 2014). "Although MAP3K8 has been reported to be an important regulator of inflammatory pathways in other diseases, the effect of MAP3K8 on obesity-induced chronic low-grade inflammation has been a point of debate." (PMID 24586913, 2014). "The function of MAP3K8 in obesity-induced inflammation has been studied previously." (PMID 24586913, 2014). "Although we cannot rule out an effect on insulin sensitivity upon specific inhibition of the MAP3K8 signalling pathway during obesity, future studies should rather illuminate the role of other inflammatory pathways and kinases in adipose tissue affecting systemic metabolic health." (PMID 24586913, 2014). "The authors showed that MAP3K8 deficient mice were not protected against the detrimental effects of diet-induced obesity." (PMID 24586913, 2014). "Together these data suggest that MAP3K8 partially affects pro-inflammatory gene expression in adipose tissue, yet does not play an important role in the development of insulin resistance during obesity." (PMID 24586913, 2014). "Moreover, systemic inflammatory markers SAA and CRP were not positively associated with increased MAP3K8 adipose tissue levels, suggestive of a redundant role of MAP3K8 in obesity-induced low-grade systemic inflammation." (PMID 24586913, 2014). "However, using mice lacking MAP3K8, our data show a redundant role for MAP3K8 in obesity-associated metabolic dysfunction." (PMID 24586913, 2014). "However, our results do not reveal any association of MAP3K8 expression with markers of insulin sensitivity in human subjects and do not support a crucial role for MAP3K8 as an important regulator in the development of insulin resistance during obesity in mice." (PMID 24586913, 2014). "Moreover, we evaluated obesity-induced adipose tissue inflammation and insulin resistance in mice lacking MAP3K8 and WT mice on a high-fat diet (HFD) for 16 weeks." (PMID 24586913, 2014). "The role of MAP3K8 in regulating the inflammatory trait of obesity is not fully clear." (PMID 24586913, 2014).
Obesity (continued). "Therefore, we propose that MAP3K8 may affect production of specific cytokines in adipose tissue inflammation during development of obesity, but that these changes do not translate to profound systemic effects." (PMID 24586913, 2014).
skin cancer (9 papers, 2013 to 2025). "In-line with this, MAP3K8−/− mice show more tumor initiation and faster progression of chemically induced skin cancer." (PMID 30463908, 2018). "In the 4th edition of the 2018 WHO classification of skin tumors, lesions in the spitzoid pathway (pathway 4) are characterized by mutations in HRAS, tyrosine kinase fusions (ALK, ROS1, RET, NTRK1/3, and MET), or serine-threonine kinase fusions (BRAF, MAP3K8)." (PMID 33040161, 2021).
thyroid cancer (7 papers, 2017 to 2026). "MAP3K8, which encodes a serine–threonine kinase, was first recognized as an oncogene in thyroid cancer." (PMID 38390852, 2024). "MAP3K8 was described as a mediator of vemurafenib resistance of thyroid cancer stem cells." (PMID 32283808, 2020).
experimental autoimmune encephalomyelitis (6 papers, 2015 to 2023). An autoimmune demyelinating disease of the central nervous system that is produced experimentally in animals by the injection of homogenized brain or spinal cord in Freund's adjuvant. "TPL-2/ERK1/2 signaling is required for cytokine and chemokine production, with TPL-2-deficient (Map3k8–/–) mice being protected in models of endotoxic shock, experimental autoimmune encephalomyelitis (EAE), pancreatitis, liver fibrosis and thrombocytopenia." (PMID 28759611, 2017).
gastric cancer (6 papers, 2015 to 2023). A primary or metastatic malignant neoplasm involving the stomach. "In this study, ChIP-seq and HiChIP-seq experiments revealed mitogen-activated protein kinase 8 (MAP3K8) to be an SE-associated gene with chromosome interactions in Epstein–Barr virus-associated gastric carcinoma (EBVaGC) cells." (PMID 36768307, 2023). "Our results indicate that super-enhancers regulate MAP3K8 expression in EBV-associated gastric carcinoma." (PMID 36768307, 2023). "The TCGA database analysis further revealed that MAP3K8 expression was directly associated with stomach adenocarcinoma stage, with patients in stages 3, 2, and 4 of stomach cancer expressing more MAP3K8 compared to the patients in stage 1 of the disease and normal patients." (PMID 36768307, 2023). "The epigenetic regulation of MAP3K8 could control gastric carcinoma progression by modulating the notch pathway and EMT." (PMID 36768307, 2023). "Further, analysis of the cancer genome atlas (TCGA) and GSE51575 databases exhibited augmented MAP3K8 expression in gastric cancer and it was found to be inversely correlated with the disease-free progression of GC." (PMID 36768307, 2023).
lung fibrosis (6 papers, 2016 to 2025). "Importantly, MAP3K8 deficiency in macrophages is associated with enhanced recruitment of inflammatory cells to the lungs and, consequently, worsened pulmonary fibrosis in mice." (PMID 37681924, 2023). "Moreover, MAP3K8 deficiency disturbs cellular metabolism in bleomycin-induced pulmonary fibrosis, as revealed by the reduced expression of COX-2." (PMID 37681924, 2023). "Taken together, an altered MAP3K8 signaling worsens pulmonary fibrosis via a COX-2-dependent metabolic mechanism, highlighting a potential protective role for MAP3K8 in IPF." (PMID 37681924, 2023). "All results impelling us to wet lab examination of MAP3K8 expression during lung fibrosis can be replicated using the Example button of Gene explorer and then filtering the DEG statistics table for lung tissue and IPF_vs_Ctrl comparisons." (PMID 34741074, 2021). "Together, these two observations provide some explanations for the increased TH2 cell responses and exacerbated hepatic and pulmonary fibrosis observed in Map3k8–/–mice." (PMID 27487182, 2016). "The decreased expression of MAP3K8 may be a contributing factor to the development of pulmonary fibrosis." (PMID 39944684, 2025). "Consistently, PGE2 levels are decreased in the absence of MAP3K8, promoting, therefore, the exacerbation of pulmonary fibrosis." (PMID 37681924, 2023). "Several of these genes (PELI1, MAP3K8, LAMA3, EMP2, CTNNAL1, CAV1, LRRK2, SFRP4) may also be involved in lung fibrosis, a severe complication of COVID-19." (PMID 37561814, 2023).